TNFRSF10B-AS1 (TNFRSF10B antisense RNA 1)
Synonyms: DR5-AS
Gene: Long non-coding RNA gene on chromosome 8 (23,068,229 to 23,083,619, forward strand). Ensembl gene ENSG00000246130.
Diseases named in the same sentence as TNFRSF10B-AS1 in open-access papers:
TNFRSF10B-AS1 is named in the same sentence as 1 disease in open-access papers, as found by Europe PMC text mining. Sharing a sentence is not in itself a finding about the gene and the disease.
TNFRSF10B-AS1 shares sentences with these, for which no sentence is quoted: cancer (1 paper).